CLSPN (claspin)
Diseases named in the same sentence as CLSPN in open-access papers (continued):
Sharing a sentence is not in itself a finding about the gene and the disease.
cancer (continued). "Functional analyses indicated that the expression TopBP1 and Claspin positively affects the survival of cancer cells and thus negatively the xenograft metastasis model animals in response to radiation." (PMID 25216549, 2014). "Our results evidenced a constant and significant increase of the rate of claspin positivity from the normal tissues to carcinomas (pχ2trend < 0.0001)." (PMID 22731782, 2012). "In conclusion, current data clearly highlight a role for Claspin in cancer." (PMID 41009395, 2025). "Adaptation to oncogene-induced RS mediated by over-expression of Claspin occurs at the expense of genome integrity and may therefore foster cancer progression." (PMID 41009395, 2025). "Nevertheless, there is also data that argues against a protective role for Claspin in cancer." (PMID 41009395, 2025). "In 2017 and 2019, we published two seminal papers discussing several ways Claspin could be involved in cancer." (PMID 41009395, 2025). "Claspin is therefore a multifunctional protein that participates in essential processes involved in the maintenance of cellular homeostasis, which is frequently altered in cancer." (PMID 41009395, 2025). "Claspin participates in several key cellular functions that are usually altered in cancer." (PMID 41009395, 2025). "Thus, the possibility that Claspin over-expression in cancer can reflect oncogenic activity also has to be considered." (PMID 41009395, 2025). "In early stages, Claspin activation may counteract tumor development, constituting an important barrier that cancer cells must overcome." (PMID 41009395, 2025). "However, other studies have shown a direct correlation between Claspin levels in tumors and worse prognosis, as well as cancer progression, features that are suggestive of a role as an oncogene." (PMID 41009395, 2025). "This way, the p38–Claspin pathway protects cells from DNA damage occurring during the S-phase, representing another resistance mechanism to cisplatin and, therefore, a potentially targetable pathway for cancer treatment." (PMID 41009395, 2025). "Therefore, cancer cells become reliant on an efficient RS response and Claspin for viability, and exploit fundamental Claspin function as an integral component of the FPC and the replisome as a way to survive." (PMID 41009395, 2025). "In addition, Claspin has been reported as a source of resistance to other anti-cancer agents, such as platinum salts (e.g., cisplatin) and bleomycin." (PMID 41009395, 2025). "Indeed, there is compelling evidence, obtained in Claspin heterozygous KO mice, that Claspin generally acts as a tumor suppressor, particularly in cancer initiation." (PMID 41009395, 2025). "These gene polymorphisms may impact the expression, function, or regulation of the CLSPN gene, thereby exerting significant effects on cancer occurrence and progression." (PMID 38256171, 2024). "As a member of anti-apoptotic proteins, the role of Bcl-2 in cancer progression has been well illustrated, whereas the biological function of Claspin in tumorigenesis remains largely unknown." (PMID 38110764, 2023). "Given the diverse functions of CLSPN, we considered that the balance of CLSPN expression could vary between benign and cancer cells, which thus dictates differential function." (PMID 36902377, 2023). "Overall, our study revealed that CLSPN might function as a potential tumor biomarker in most cancers, especially in LUAD." (PMID 37268895, 2023). "Therefore, we should spare more efforts to investigate the specific role of CLSPN in different cancers." (PMID 37268895, 2023). "In addition, the relationships between CLSPN and four methyltransferases were also observed in the majority of cancer types." (PMID 37268895, 2023). "Moreover, the role of CLSPN in cancer was validated by CCK-8, EDU, colony formation and flow cytometry in vitro and tumor cell derived xenograft model in vivo." (PMID 37268895, 2023).
cancer (continued). "In general, our study systematically analyzed the functions of CLSPN, which might provide potential therapeutic strategies for cancers." (PMID 37268895, 2023). "Knockdown CLSPN significantly inhibited cancer cell growth both in vitro and vivo experiments." (PMID 37268895, 2023). "We explored whether CLSPN expression was related with stemness score in a variety of cancers by conducting a correlation analysis." (PMID 37268895, 2023). "Finally, this work also identifies a novel role for Claspin, an important Chk1 activator, in female fertility and cancer development, furthering our understanding of how dysfunction in the Claspin/Chk1 signaling pathway affects disease states." (PMID 36416754, 2022). "We, therefore, next investigated whether CLSPN mRNA levels are also predictive of cancer progression in humans." (PMID 36240068, 2022). "Nonetheless, these data suggest that Claspin levels can be a prognostic cancer indicator and importantly could influence the response to therapy, particularly of checkpoint kinase inhibitors, in human patients." (PMID 36240068, 2022). "Aberrant increase in expression of claspin has been observed in cancer." (PMID 35386989, 2021). "We performed qRT‐PCR to confirm whether the CLSPN gene is cancer specific in 14 types of normal tissue and 28 PCa tissues obtained from radical prostatectomy specimens." (PMID 34240817, 2021). "Moreover, a recent study has shown that Timeless upregulation together with Claspin can protect cancer cells from oncogene-induced replication stress depending on a checkpoint-independent mechanism." (PMID 33971927, 2021). "In fact, there is a considerable body of evidence linking Claspin deregulation with cancer." (PMID 32847043, 2020). "Due to the role of Claspin in overall cell homeostasis, it is reasonable to hypothesize that CLSPN genetic variants that affect Claspin function may play a role in cancer development." (PMID 32847043, 2020). "As for the genotypic and allele frequencies of CLSPN c.-68C>T, c.17G>A, c.2230T>C, c.3595-3597delGAA and c.3839C>T variants, no major differences were detected between controls and cancer patients." (PMID 32847043, 2020). "Acting through a mechanism independent of its checkpoint function, when overexpressed in cancer cells, Claspin participates in a replication fork protection mechanism, which alleviates oncogene-driven replication stress and allows fork progression and, hence, cancer cell replication." (PMID 32847043, 2020). "Interestingly, Claspin overexpression, in coordination with that of Timeless, appears to constitute a cancer survival mechanism." (PMID 32847043, 2020). "With the exception of CLSPN c.17G>A (p.Gly6Asp), which did not present a significant association with cancer and was not predicted to have a functional impact, the impact of all other variants on splicing was studied using minigene assays." (PMID 32847043, 2020). "However, the mechanism by which Claspin, Timeless, and Tipin promote cancer progression is currently unclear." (PMID 30796221, 2019). "USP7 is also involved in other cancer-associated mechanisms such as DNA damage and repair, epigenetic regulation, human terminal erythoid differentiation and immune responses by regulating other cancer-related targets such as N-Myc, FOXO, PTEN and Claspin." (PMID 31730000, 2019). "In this context, enhanced levels of Claspin, Timeless, and Tipin in cancer cells may promote the reassembly of the FPC and accelerate fork restart." (PMID 30796221, 2019). "Interestingly, this requirement for Claspin is specific to normal cells, and cancer cells appear to have acquired mechanisms that bypass this pathway." (PMID 27401717, 2016). "It has been shown that claspin positively affects the survival of cancer cells." (PMID 26244918, 2015). "In the present study, we took our analysis one step further investigating whether claspin expression was differently modulated in the dysplastic lesions that precede the cancer." (PMID 22731782, 2012).
cancer (continued). "Therefore, starting from the WNL tissues through to carcinomas, we observed a constant and significant increase of claspin expression (pχtrend2 < 0.0001)." (PMID 22731782, 2012). "Therefore, it is possible that Claspin over-expression in different tumors may just reflect an adaptive behavior of cancer cells to promote survival in response to high levels of RS, rather than suggesting a direct role for Claspin in disease severity." (PMID 41009395, 2025). "However, as oncogenesis progresses and replication stress (RS) increases, cancer cells may start to exploit the RS response, in which Claspin plays a pivotal role." (PMID 41009395, 2025). "In addition, Claspin inactivation may facilitate cancer dedifferentiation, as Claspin is required for transmission of the histone code during cell division and for epigenetic memory." (PMID 41009395, 2025). "Hunter and colleagues proposed that, in the early stages of carcinogenesis, CLSPN is a nuclear factor-kappa B (NF-kB) target gene that helps to prevent or reduce genome instability through its role in Chk1 activation, and therefore acts as a barrier in cancer development that results from RS." (PMID 41009395, 2025). "Indeed, there is a considerable body of evidence linking Claspin deregulation with cancer." (PMID 41009395, 2025). "As Claspin has a role in several processes involved in the maintenance of genome integrity and the promotion of successful and uneventful cell division, it is plausible that it may have a role in cancer development." (PMID 41009395, 2025). "However, as the process progresses to overt cancer, Claspin expression increases." (PMID 41009395, 2025). "Therefore, Claspin may have a more complex role in cancer than previously anticipated, which may be dependent on the cellular context, the mutational landscape of tumors, and the stage of oncogenesis." (PMID 41009395, 2025). "Changes in Claspin expression levels may be used as a prognostic marker in several types of cancer." (PMID 41009395, 2025). "There is also data arguing against this hypothesis, showing that upstream and downstream components of the ATR–Chk1 pathway are differentially regulated in primary cancer cells, and that Claspin, Tim, and Chk1 make part of a functional module that functions independently of the ATR axis." (PMID 41009395, 2025). "Furthermore, CLSPN expression was found to correlate with immune cell infiltration levels, tumor mutational burden (TMB), microsatellite instability (MSI), mismatch repair (MMR) gene, DNA methylation and stemness score across 33 types of cancer." (PMID 37268895, 2023). "Moreover, elevated CLSPN expression was closely correlated with immune cells infiltration, TMB (tumor mutational burden), MSI (microsatellite instability), MMR (mismatch repair), DNA methylation and stemness score across 33 cancer types." (PMID 37268895, 2023). "Thus, Claspin may play a role for the activation of this essential signaling pathway during normal growth of cancer cells." (PMID 36671510, 2023). "Therefore, the insights afforded by our structure could potentially be exploited to generate inhibitors of CLASPIN and TIMELESS replisome association for anti‐cancer therapy." (PMID 34694004, 2021). "Given that loss of APC/CCdh1 activity is associated with genomic instability and tumorigenesis it is tempting to speculate that upregulation of Claspin, Chk1, Cyclin A, and Plk1 may contribute to genomic instability and cancer, in part, via antagonism of APC/CCdh1." (PMID 32345958, 2020). "It is conceivable that Claspin gene (CLSPN) alterations may contribute to cancer development." (PMID 32847043, 2020).
cancer (continued). "Indeed, this is exemplified by CLSPN which may have therapeutic potential as its gene product, Claspin, has recently been shown to have a broader role in cancer cell viability by protecting cancer cells from replication stress." (PMID 32880368, 2020). "Therefore, GSK3-β inhibition as a therapy in cancer cells could be promoting undesired survival via Claspin stabilization and Chk1 activation." (PMID 31362447, 2019). "Therefore, we can hypothesize that claspin identifies almost all the high grade lesions and cancers." (PMID 22731782, 2012). "Claspin may act as a tumor suppressor at the initial phases of malignant transformation, protecting the cell from oncogenic pressure, but it is possible that in the later stages of carcinogenesis, it may acquire oncogenic properties, fostering cancer progression and survival." (PMID 41009395, 2025). "In turn, primary fibroblasts that escaped oncogene-induced senescence presented over-expression of Claspin and Tim, two components of the FPC, further supporting the notion of of cancer cells adapting to RS." (PMID 41009395, 2025). "A similar therapeutic approach can be envisioned targeting Claspin, since, due to RS, the ATR–Claspin–Chk1 pathway is often over-activated in cancer cells." (PMID 41009395, 2025). "For the ALT high and TELlow phenotype, the BRIP1 and CLSPN genes were upregulated in 12 different cancer types and the MTND1P23 pseudogene was downregulated in 14 cancer types, and SCGB3A1 in 12 cancer types." (PMID 38763334, 2024). "Claspin facilitates initiation by recruiting Cdc7 and thereby promoting MCM phosphorylation, notably in non-cancer cells." (PMID 39194567, 2024). "Substantial variations in both the basal expression (ATR, Claspin, Chk1, and Rad51) and agonist-induced activation (p-Chk1) of DDR components were observed in canine cancer cell lines." (PMID 37655260, 2023). "The downexpression of these miRNAs significantly reduced cancer cell proliferation and apoptosis by targeting FOXO-3, CLSPN, ACVR1B, E2F4 and PPP2CA and regulated cell cycle progression by targeting CDKN2A and FOXO-3." (PMID 34743742, 2021). "Cancers displaying unfavorable risk with high ALT (BRCA, SARC, and LUAD) may be regulated by the transcriptional factors E2F4, TFDP1, E2F1, E2F7, and SIN3A (FDR = 0.001) in the DNA repair pathway, including genes repairing DNA damage such as CENPI, CLSPN, TOPBP1, and MCM4." (PMID 32784588, 2020). "Dunphy’s group previously reported that casein kinase 1 γ1 (CK1γ1) can promote interaction between Claspin and Chk1 through phosphorylating CKBD in cancer cells." (PMID 31889509, 2019). "Here, the authors report that cancer cells adapt to oncogene-induced RS by overexpressing downstream components of ATR-CHK1 pathway, Claspin and Timeless, which have protective role at the replication forks independent of their checkpoint function." (PMID 30796221, 2019). "Together, these data indicate Claspin, Timeless, and CHK1 are frequently overexpressed in primary cancers independently of upstream components of the ATR-CHK1 pathway." (PMID 30796221, 2019). "We found that unlike the checkpoint sensors ATR, RAD9, and RAD17, the downstream components of the ATR pathway Claspin, Timeless, and CHK1 show a correlated overexpression in cancer cells." (PMID 30796221, 2019). "In particular, while the minimum number of claspin-positive nuclei/HPF was almost the same in all the histological categories, the maximum value significantly increased from normal cervix to carcinomas." (PMID 22731782, 2012). "Although our study is the first to comprehensively unveil the polytrophic functions of CLSPN in cancer, there is not without limitations." (PMID 37268895, 2023).
cancer (continued). "Claspin knockdown increased phosphorylation of MAP kinases including p38 MAPK, SAP1/JNK1, and ERK1/2 in cancer cells, suggesting it may negatively regulate the MAP kinase pathways during unperturbed growth." (PMID 36671510, 2023). "Many cancer cells present higher expression of the components of the ATR-Claspin-Chk1 pathway, as compared with non-cancerous cells, which can be related to resistance to radiotherapy." (PMID 37655260, 2023). "The ATR-Chk1-Claspin pathway has been found to be upregulated in cancer cells, as compared with non-cancerous cells in humans, therefore its inhibition presents an attractive target for new-generation cancer therapies." (PMID 37655260, 2023). "Interestingly, overexpression of CLASPIN and TIMELESS protects cancer cells from replication stress making them promising anti‐cancer targets." (PMID 34694004, 2021). "Claspin is a critical protein for the ATR‐CHK1 pathway, so cancer cells may more sensitive under the inhibition of claspin." (PMID 34240817, 2021). "To determine how Claspin, Timeless, and CHK1 could promote tolerance to RS independently of ATR signaling, we first checked their protein levels in cancer cell lines and immortalized primary cells." (PMID 30796221, 2019). "Next, we asked whether protein levels of Claspin, Timeless, and CHK1 are correlated in cancer cell lines." (PMID 30796221, 2019). "Despite these findings, to date no data are available concerning claspin expression in human cervical carcinogenesis which represents a paradigmatic model of cancer development." (PMID 22731782, 2012). "Upon genotoxic stress, HNF-1β prevents Claspin ubiquitin-mediated proteasomal degradation through the action of USP28, therefore promoting Claspin stabilization, and inducing Chk1 activation and G2 cell cycle arrest, which provides cancer cells more time to repair DNA damage and survive." (PMID 41009395, 2025). "Given its crucial functions, a role for Claspin in cancer is not a surprise." (PMID 41009395, 2025). "However, a multi-omics pan-cancer analysis on the function of CLSPN from the comprehensive angle has not been reported yet." (PMID 37268895, 2023). "However, high Claspin mRNA levels correlate with poor survival in human cancer, although these data reflect the situation in end-stage tumours rather than any role for Claspin in the earlier stages of tumorigenesis." (PMID 36240068, 2022). "Although Claspin is an essential gene for the maintenance of cell viability and homeostasis, the use of Claspin inhibitors may still be viable and achievable without too much (or acceptable) toxicity to healthy cells due to the intrinsic features of cancer cells that are absent in healthy ones." (PMID 41009395, 2025). "Bianco and colleagues have shown that different clones of cancer cells acquired different properties and adopted distinct strategies to cope with RS, some of which could not be fully explained by over-expression of Claspin and Tim." (PMID 41009395, 2025). "Therefore, over-expression of Claspin (and other FPC components) in cancer cells may constitute a reservoir of these proteins that allows the fast reassembly of functional FPCs that will promote fork restart and RS tolerance by a mechanism independent of the ATR-Chk1 checkpoint signaling pathway." (PMID 41009395, 2025). "However, a comprehensive analysis of CLSPN in cancers has not been conducted." (PMID 37268895, 2023). "The researchers reasoned that previous reports correlating increased Claspin expression in cancers may be adaptive to promote cell survival in response to the high degree of replication stress, rather than suggesting a direct role of Claspin in disease severity." (PMID 36416754, 2022). "Smo inhibition sensitizes cancer cells to radiation, as in this situation, USP3 is not expressed, and Claspin is polyubiquitylated and degraded in the proteasome." (PMID 41009395, 2025).